MIR339 (microRNA 339)
Synonyms: hsa-mir-339; MIRN339; mir-339
Gene: MicroRNA gene on chromosome 7 (1,022,933 to 1,023,026, reverse strand). Ensembl gene ENSG00000199023.
Gene Ontology:
Biological process: miRNA-mediated post-transcriptional gene silencing
Cellular component: RISC complex
Homologues: Orthologues: chimpanzee ptr-mir-339 (99% identical), macaque mml-mir-339 (99% identical), mouse Mir339 (81% identical), guinea pig MIR339 (79% identical), rat Mir339 (79% identical), pig ssc-mir-339-1 (64% identical), dog MIR339 (51% identical), pig ssc-mir-339-2 (46% identical).
Diseases named in the same sentence as MIR339 in open-access papers:
MIR339 is named in the same sentence as 4 diseases in open-access papers, as found by Europe PMC text mining. Sharing a sentence is not in itself a finding about the gene and the disease. The quoted sentences say what the papers report.
leukemia (1 paper, 2024). A malignant (clonal) hematologic disorder, involving hematopoietic stem cells and characterized by the presence of primitive or atypical myeloid or lymphoid cells in the bone marrow and the blood. "Interestingly, MIR339 overexpression has been tied to the development of cancer by increasing cell viability and decreasing pro-apoptotic gene expression in stem cell leukemia/lymphoma cells." (PMID 38554160, 2024).
MIR339 also shares sentences with these, for which no sentence is quoted: cancer (1 paper); lymphoma (1); metastatic tumors (1).